STAT3 (signal transducer and activator of transcription 3)
Diseases named in the same sentence as STAT3 in open-access papers (continued):
Sharing a sentence is not in itself a finding about the gene and the disease.
hepatocellular carcinoma (continued). "In a study on hepatocellular carcinoma (HCC), IL-11 was shown to promote tumor cell proliferation and resistance to apoptosis by activating the STAT3 signaling pathway, contributing to cancer recurrence in postoperative HCC patients." (PMID 39421736, 2024). "Trillin inhibits autophagy and promotes apoptosis in hepatocellular carcinoma cells through activation of the mTOR/STAT3 signaling pathway, suggesting its potential as a therapeutic agent for HCC." (PMID 39315094, 2024). "In addition, NF-κB induces the release of the inflammatory factor IL-6, leading to the signal transducer and activator of STAT3 activation, which promotes hepatocyte repair and replication capacity and inhibits apoptosis, thereby promoting the development of hepatocellular carcinoma." (PMID 38313314, 2024). "IL-6 promotes PD-L1 expression in human hepatocellular carcinoma (HCC) through the JAK/STAT3 signaling pathway, thereby reducing the expression of protein tyrosine phosphatase receptor and further promoting tumor immune escape." (PMID 39286258, 2024). "Conversely, it was found that upon inhibition of mTOR in macrophages in hepatocellular carcinoma (HCC), STAT3 decreased the secretion of both IL-10 and IL-12 and inhibited angiogenesis in vivo." (PMID 39003350, 2024). "In in vitro experiments with co-cultured TAMs and hepatocellular carcinoma cells it was shown that M2-like cells produce IL-8 which upregulates EMT markers in HCC cells via the JAK2/STAT3 pathway." (PMID 38794298, 2024). "Additionally, this research demonstrates that CKLF1 mediated its oncogenic effects through the IL-6/STAT3 signaling pathway and could assist in the staging and prognostic assessment of patients with hepatocellular carcinoma." (PMID 36865551, 2023). "In patients with advanced hepatocellular carcinoma (HCC), STAT3 knockdown promotes endoplasmic reticulum stress-induced apoptosis induced by sorafenib." (PMID 37920470, 2023). "Quercetin could exert antitumor effects by preventing hepatocellular carcinoma LM3 cells from proliferating, migrating and invading, causing cell cycle arrest and apoptosis and stimulating HCC autophagy via abrogating the JAK2/STAT3 signaling pathway (by downregulating JAK2 and STAT3)." (PMID 36837850, 2023). "In the case of human hepatocellular carcinoma (HCC), TAM (tumor-associated macrophage)-derived IL-37 impedes their polarization towards the M2 phenotype by affecting the IL-6/STAT3 axis, eventually inhibiting the growth of the tumor." (PMID 37298214, 2023). "In addition, in this study, WCP was discovered to inhibit hepatocellular carcinoma, possibly by promoting apoptosis through the promotion of Cyto-c/Caspase8/3 and inhibition of IL-10/STAT3/Bcl2 signaling pathways, which will advance our understanding of WCP as a potential therapeutic option for HCC." (PMID 37110586, 2023). "Metformin promotes ferroptosis and sensitivity to sorafenib in hepatocellular carcinoma cells via ATF4/STAT3, and it inhibits HCC progression." (PMID 37326750, 2023). "A juglone analogue (compound 107) isolated from the root of Polygonum cuspidatum inhibited the growth of hepatocellular carcinoma (HCC) and HCC cancer stem cells via the blockage of the STAT3 signaling pathway." (PMID 36500400, 2022). "In hepatocellular carcinoma (HCC), the signal transducer and activator of transcription 3 (STAT3) is present in an overactive state that is closely related to tumour development and immune escape." (PMID 35665592, 2022). "STAT3 is a well-studied transcription factor antagonizing proinflammatory signals during innate immune response, and is known to regulate expression of miRNAs in human hepatocellular carcinoma cells and T-helper 17 cells, so expression of STAT3 and its phosphorylated form were examined." (PMID 34563711, 2022). "In previous human studies, nuclear phospho-STAT3 (Tyr705) was immunoreactive in 37–67% of head and neck squamous cell carcinoma samples and 49.3% of hepatocellular carcinomas (HCC)." (PMID 35836213, 2022).
hepatocellular carcinoma (continued). "This action is carried out by the suppression of the signaling mediated by the cytokine IL-6 in macrophages and hepatocellular carcinoma cells (HCC), through STAT3 inhibition." (PMID 36004343, 2022). "A study explored the effects of CK on liver cancer in HepG2 cells, SMMC‐7721 cells, and mice‐bearing human hepatocellular carcinoma (HCC) xenografts, indicating that CK decreased the DNA‐binding capacity of STAT3 in HepG2 and SMMC‐7721 cells." (PMID 34793617, 2022). "Besides, transformed hepatocytes rely on STAT3 expression in hepatocellular carcinoma, and iExosomes targeting STAT3 in liver could also offer benefits in attenuating progression." (PMID 36120332, 2022). "NIC inhibits the proliferation of hepatoma cells by inhibiting STAT3 signaling, thereby increasing the chemosensitivity of hepatocellular carcinoma (HCC) cells." (PMID 36555754, 2022). "As a novel anti-cancer molecule, icaritin has been shown to suppress hepatocellular carcinoma (HCC) initiation and malignant growth through the Interleukin-6/Janus-activated kinases 2/Signal transducer and activator of transcription 3 pathway." (PMID 34068926, 2021). "The results showed that HBX could activate PI3-K, ERK, STAT3, and NF-κB pathways in hepatoma cells." (PMID 33722250, 2021). "Moreover, STAT3 is specifically associated with the promoter of HOXD-AS1 and then activates HOXD-AS1 transcription, resulting in a poor prognosis and advanced stage of lymph node metastasis in hepatocellular carcinoma patients." (PMID 34867344, 2021). "Persistent activation of STAT3 is observed in human malignancies, including hepatocellular carcinoma (HCC) and multiple myeloma (MM)." (PMID 34771643, 2021). "Finally, CCT3 knockdown could reduce both total and phosphorylated STAT3 levels in hepatocellular carcinoma HepG2 cells." (PMID 34612768, 2021). "The root extract of Polygonum cuspidatum consisting of 2-ethoxystypandrone, i.e., a novel analogue of juglone, was shown to exhibit inhibition of the STAT3 signaling pathway in hepatocellular carcinoma cells (HCC cells)." (PMID 34358102, 2021). "Furthermore, related researches have proved that upregulated ROS could abrogate JAK2/STAT3 signaling to suppress tumor growth in cancers such as hepatocellular carcinoma, multiple myeloma, and colorectal cancer." (PMID 32576206, 2020). "In hepatocellular carcinoma, in vitro and in vivo studies reveal that simvastatin induces G0/G1 arrest by upregulating p21 and p27, activating AMPK and inhibiting the STAT3-Skp2 axis in HCC." (PMID 32974183, 2020). "Blocking either CAF IL-6 or myeloid STAT3 can disrupt signaling from CAFs to myeloid cells and attenuate immunosuppression in hepatocellular carcinoma (HCC) and pancreatic cancer." (PMID 33370234, 2020). "The hepcidin-stimulating effects of vorinostat in Huh7 hepatoma cells were also validated in another study, and are consistent with earlier data showing that the histone deacetylase inhibitor trichostatin A induces hepcidin by inhibiting the binding of C/EBPα and STAT3 in the HAMP promoter." (PMID 30469435, 2018). "Dovitinib, a multi-targeted receptor kinase inhibitor, was shown to directly and effectively induce SHP1 activity, leading to decreased STAT3 phosphorylation, the inhibition of hepatocellular carcinoma (HCC) growth, and an increase in apoptosis." (PMID 30208623, 2018). "A recent study has suggested that arecoline can reduce IL-6 and STAT3 in a human hepatoma cell line at concentrations of 0, 3, 30 and 100 μg/ml: in contrast, we found that arecoline treatment at 0.025 μg/ml could upregulate IL-6 and STAT3 mRNA expression in ORL-48(T) cells." (PMID 29385191, 2018).
hepatocellular carcinoma (continued). "Among the tested compounds, 16 reduced the level of phospho-STAT3, inhibited the downstream signalling cascade and subsequently attenuated the survival of hepatocellular carcinoma (HCC) cells." (PMID 30261753, 2018). "Aberrant methylation of SOCS1 silences SOCS1 and activates the JAK2/STAT3 pathway in hepatocellular carcinoma cells (HCC), resulting in the development of HCC." (PMID 30285793, 2018). "Moreover, curcumin could suppress vasculogenic mimicry capacity of hepatocellular carcinoma cells through STAT3 and PI3K/AKT inhibition." (PMID 30186159, 2018). "Recently, Chen and his colleagues demonstrated that EMT and progression of hepatocellular carcinoma (HCC) is effectively modulated by SHP-1 via suppression of TGF-β1-induced constitutive p-STAT3 activity." (PMID 29409467, 2018). "Our previous data demonstrated that lncRNA DANCR, which was first identified in hepatocellular carcinoma (HCC), promoted the cell proliferation and chondrogenic differentiation through up-regulating the expression of Smad3 and STAT3." (PMID 28674107, 2017). "Hepatocellular carcinoma (HCC) cells, H22 and Hepa1–6, were modified by blocking the STAT3 signaling pathway with a STAT3 decoy oligodeoxynucleotide, and the immunogenicity and possibility of using these cell lysates as a vaccine were evaluated." (PMID 29115974, 2017). "Furthermore, STAT3 signaling has been identified to promote the progression and metastasis via inducing cancer stem cell-like properties in variety of cancers, including hepatocellular carcinoma." (PMID 28750679, 2017). "Studies of hepatocellular carcinoma have shown that IL-17E activates the NFκB and Jak/STAT3 signaling pathways in cancer stem cells, thus resulting in tumor growth and progression and suggesting that IL-17E/IL-17RB may be a therapeutic target in the treatment of this disease." (PMID 27462789, 2016). "In addition, hepatocyte-specific STAT3-deficient mice exhibited markedly greater resistance to hepatocellular carcinoma and the tumor sizes were evidently smaller, suggesting that STAT3 is crucial in promoting hepatocellular carcinoma cell proliferation and/or survival." (PMID 25360179, 2014). "Furthermore, ROS production in hepatoma cells infected with Hepatitis C virus (HCV) activated STAT3 through JAK, Src kinase, and p38 MAP kinase pathways, and the decreased phosphorylation of p38 MAPK blocks the oxidative stress-induced senescence of myeloid leukemic cells." (PMID 23573126, 2013). "In the docking model, it binds with SH2-domain of STAT3 and prevents STAT3 phosphorylation at Tyr705, leading to inhibition of downstream STAT3 activities and apoptosis in multiple cancer cell lines including breast, pancreatic, hepatocellular carcinoma and rhabdomyosarcoma (IC50 ≈ 15-50 μM)." (PMID 24308725, 2013). "Studies confirm its regulatory influence over hepatocellular carcinoma progression through SIRT1 modulation and its intimate link with hepatoblastoma via angiogenic control mediated by the JAK2/STAT3 pathway." (PMID 41523988, 2026). "Subsequent examinations of BSCA-activated hepatocellular carcinoma cells revealed alterations in the gene expression of JAK2 and STAT3, as well as changes in the levels of p-JAK2 and p-STAT3 proteins." (PMID 39940837, 2025). "Acquired lenvatinib resistance in hepatocellular carcinoma was driven by an EGFR/STAT3 axis, where STAT3 directly bound the ABCB1 promoter to upregulate P-gp and enhance drug efflux, and inhibiting either EGFR or STAT3 restored drug sensitivity." (PMID 41373605, 2025). "Cancers with elevated STAT3 activity include renal cell carcinoma, colorectal cancer, ovarian carcinoma, gastric carcinoma, breast cancer, lung cancer, hepatocellular carcinoma (HCC), pancreatic adenocarcinoma, and head and neck squamous cell carcinoma." (PMID 39792482, 2025).
hepatocellular carcinoma (continued). "Previous studies have demonstrated that ZZXJD induces autophagy and apoptosis in hepatocellular carcinoma cells via the AKT/mTOR and JAK2/STAT3 signaling pathways, resulting in programmed cell death and inhibition of HCC progression." (PMID 40303917, 2025). "In hepatocellular carcinoma, FMRP regulates the localization and translation of signal transducer and activator of transcription 3 (STAT3) mRNA and accelerates hepatocellular carcinoma metastasis." (PMID 40271197, 2025). "In conclusion, our study suggests that BSCAs can induce apoptosis in hepatocellular carcinoma cells and modulate the JAK2/STAT3 signaling pathway in hepatocellular carcinoma cells." (PMID 39940837, 2025). "STAT3, a member of the STAT protein family, has been reported to regulate NMDAR transcription and is regulated by SH2D5 in hepatocellular carcinoma." (PMID 40857409, 2025). "The results suggest that compounds derived from C. lancifolius, particularly Alnusiin, may serve as potential inhibitors of CASP3 and STAT3 proteins in hepatocellular carcinoma (HCC) and could be explored for the development of improved anti-HCC therapeutics." (PMID 40599803, 2025). "Hepatocellular carcinoma patients derived CAFs (HCC-CAFs) release IL-6, stimulating PD-L1 expression on neutrophils via the STAT3 pathway." (PMID 39287890, 2025). "In hepatocellular carcinoma (HCC), HBV-driven tumors suppress miR-200c via TGF-β/STAT3 signaling, which in turn elevates PD-L1, while reintroduction of miR-200c reduces PD-L1 expression and reinvigorates T cells." (PMID 40647470, 2025). "GYY4137 demonstrated its ability to suppress tumor growth in hepatocellular carcinoma (HCC) cells and in a HepG2 xenograft model by targeting the STAT3 pathway." (PMID 40445424, 2025). "Furthermore, in hepatocellular carcinoma (HCC), IL‐6 derived from CAFs recruits neutrophils through the STAT3/PD‐L1 signaling pathway." (PMID 41164803, 2025). "Subsequent experiments demonstrated that neutralizing OSM activity with a specific antibody markedly suppressed N‐CM‐induced STAT3 activation and inhibited the EMT process in hepatoma cells." (PMID 39932456, 2025). "For instance, the relationship between cancer development and inflammation was studied using a hepatocellular carcinoma model, examining the occurrence of Treg cells in the TME and STAT3 activation." (PMID 40420174, 2025). "In human hepatocellular carcinoma cell lines, GADD45G expression strongly suppresses constitutive phosphorylation of STAT3 (Tyr705)." (PMID 38504984, 2024). "In hepatocellular carcinoma, eEF2K promotes angiogenesis via the PI3K/Akt and STAT3 signaling pathways." (PMID 39592671, 2024). "For example, GH excess triggers the activation of signal transducer and activator of transcription 3 (STAT3) and Janus kinase (JAK) in the development of hepatocellular carcinoma." (PMID 37584889, 2024). "By stimulating ROS‐mediated MAPK, STAT3, and NF‐B signaling pathways, calycosin inhibited the expression of TGF‐1, SMAD2/3, SLUG, and vimentin and resisted hepatocellular cancer." (PMID 38230908, 2024). "As a result, methylation of STAT3 by PRMT1 activates STAT3-mediated signaling pathways, leading to the progression and metastasis of several cancers, such as GBM and hepatocellular carcinoma." (PMID 38474197, 2024). "(2009), hepatoma cells and hepatocytes stimulated with IL-27 displayed sustained activation of STAT-1 and STAT-3, leading to an IFN-γ-like STAT-1-dependent response." (PMID 38720890, 2024). "The Cancers Editorial Office retracts the article, "MicroRNA-21 Plays Multiple Oncometabolic Roles in the Process of NAFLD-Related Hepatocellular Carcinoma via PI3K/AKT, TGF-β, and STAT3 Signaling" [...]." (PMID 38672694, 2024). "For instance, DDR2 expression is upregulated in oxaliplatin-resistant hepatocellular carcinoma cell lines and induces chemoresistance by inducing C-C motif chemokine ligand 20 (CCL20) via STAT3 activation." (PMID 39766183, 2024).
hepatocellular carcinoma (continued). "In hepatocellular carcinoma (HCC), M2 macrophages promote HCC cell migration and EMT via the TLR4/STAT3 signaling pathway." (PMID 38213716, 2024). "For this purpose, four cell lines, representative of breast, lung, prostate, and hepatocellular cancers, were treated with β-HCH, specific tyrosine kinase inhibitors (TKIs), and a STAT3 inhibitor." (PMID 38892372, 2024). "In hepatocellular carcinoma, the activation of the CXCL12/CXCR4 axis via the STAT3 signaling pathway promotes protein expression of CSC markers SOX2 and CD133, enhancing the spheroid-forming capacity and invasiveness of liver cancer cells." (PMID 38920657, 2024). "Another interesting research proved that absence of IKKβ causes STAT3 activation, leading to upregulated ROS accumulation in mouse hepatocellular carcinomas (HCC), and inverse relationships between the activation of NF-κB and STAT3 have also been observed in human HCC." (PMID 39493763, 2024). "In a nude mouse xenograft model of hepatocellular carcinoma, combination treatment with cisplatin and YC1, a down regulator of STAT3, suppressed tumor growth compared to treatment with cisplatin alone." (PMID 38339245, 2024). "STAT3 inhibitor, TTI-101, recently gained a fast-track designation from the FDA for the treatment of hepatocellular carcinoma (NCT03195699)." (PMID 39768178, 2024). "In hepatocellular carcinoma, NOD2 activates AMPK, MAPK, NF-κB, STAT3, and ERK pathways and induces nuclear autophagy directly through Lamin A/C." (PMID 39353904, 2024). "Previous studies have shown that the overexpression of PTGS2 is mediated by STAT3, and the inactivation of STAT3 is accompanied by the decreased expression of PTGS2 in hepatocellular carcinoma." (PMID 39125712, 2024). "By contrast, the inhibition of IL-6/signal transducer and activator of transcription 3 (STAT3) signaling reduced cancer recurrence in preclinical models of breast, head and neck, and hepatocellular carcinoma." (PMID 38234925, 2023). "AZD9150, a STAT3 ASO, is undergoing phase 1 clinical trials for patients with advanced hepatocellular carcinoma (HCC) [NCT01839604] as well as advanced solid malignancies [NCT03394144]." (PMID 37305676, 2023). "In gastric cancer and hepatocellular carcinoma, AOC1 functions as an oncogene, either by activating the AKT signaling pathway and EMT or by regulating the IL-6/JAK/STAT3 pathway." (PMID 37525249, 2023). "For example, in hepatocellular carcinoma, TGF-β produced by TAMs induced NF-κB, AKT and STAT3 signaling pathways in CSCs, thus enhancing HCC stemness and epithelial to mesenchymal transition." (PMID 36910604, 2023). "Some studies have demonstrated that the Janus-activated kinase 2 (JAK2)/signal transducer and activator of transcription 3 (STAT3) pathway are correlated with tumor progression, such as gastric cancer, colorectal cancer, and hepatocellular carcinoma." (PMID 36814203, 2023). "The three signaling molecules formed the HIF-1α/STAT3/VEGF signal transduction pathways, which played an important role in the occurrence and development of hepatocellular carcinoma." (PMID 37333486, 2023). "In human non-small cell lung cancer and human hepatocellular carcinoma, morusin can induce apoptosis through EGFR/STAT3 or IL-6/STAT3 signaling pathway to play an anti-cancer effect." (PMID 37386395, 2023). "In malignant tumors, niclosamide inhibits Wnt/β-catenin, STAT3, mTOR, NF-κB, and the BCL2 family to induce tumor cell death in adrenocortical carcinoma, lung cancer cells, leukemia, hepatocellular carcinoma, and breast cancer." (PMID 37627178, 2023). "Studies showed that the overexpression of STAT3 and VEGF in tumor cells can increase the microvessel density and promote the progression of hepatocellular carcinoma." (PMID 37333486, 2023). "Our results indicate that curcumin suppressed hepatocellular carcinoma cell migration by disturbing the cell cycle and transduction signal pathways HIF-1α/STAT3/VEGF." (PMID 37333486, 2023).